RGS5 (regulator of G protein signaling 5)
Diseases named in the same sentence as RGS5 in open-access papers (continued):
Sharing a sentence is not in itself a finding about the gene and the disease.
hepatocellular carcinoma (6 papers, 2016 to 2024). A malignant tumor that arises from hepatocytes. "Overexpression of RGS5 has been detected in hepatocellular carcinoma and is associated with cancer recurrence, venous infiltration, and poorer survival." (PMID 27105500, 2016). "RGS5 is reportedly related to the invasion and metastasis of cancers, such as nonsmall lung cancer and hepatocellular carcinoma." (PMID 31049219, 2019). "RGS5 is highly expressed in malignant tumors, and overexpression of RGS5 promotes tumor metastasis by inducing epithelial-mesenchymal transition in hepatocellular carcinoma." (PMID 29158988, 2017). "RGS5 is highly expressed in most hepatocellular carcinoma tissue samples and cell lines." (PMID 37924113, 2023). "In addition, Rgs5 expression in rodents promotes portal vein invasion and intrahepatic metastasis from hepatocellular carcinoma." (PMID 36687508, 2022). "There is evidence that RGS5 may be involved in the regulation of GSK-3β activity and Wnt/β-catenin signalling, affecting the development of hepatocellular carcinoma." (PMID 37924113, 2023).
breast carcinoma (5 papers, 2023 to 2025). "Pericytes in human breast cancer, defined by the expression of RGS5, have previously been shown to have gene expression patterns similar to those of CAFs21." (PMID 37463917, 2023). "In contrast, VSMCs were treated with BC-CM from RGS5 knockdown breast cancer cells reversed the upregulation of TNF-α, VCAM-1 and macrophages adhesion." (PMID 37986113, 2023). "To determine the relationship between RGS5 expression and remodeling of the vasculature in the tumors, we examined the sections of human breast cancer tissues by immunohistochemical staining." (PMID 37986113, 2023). "However, in the context of breast cancer tissues, the role of RGS5 was completely disrupted, which mediated VSMC inflammation and vascular remodeling in the tumor tissues." (PMID 37986113, 2023). "In contrast, in the context of breast cancer tissues, the role of RGS5 was completely disrupted." (PMID 37986113, 2023). "These metabolites can act through intervening in breast cancer targets such as SARM1, RGS5, BAG1, PROM2, and NEAT1." (PMID 40223933, 2025). "Reclustering of the COL1A1-positive CAFs and removal of RGS5-positive pericytes resulted in four CAF subpopulations, of which the two major clusters (cluster 1 and 2) expressed iCAF and myCAF gene signatures, respectively, confirming the presence of iCAFs and myCAFs in human breast cancer." (PMID 36635273, 2023).
ischemic stroke (5 papers, 2016 to 2025). A stroke disorder caused by obstruction of blood flow to the brain, due to thrombotic (local blood clot formation) or embolic (due to a blood clot or other material traveling from another site) event. "RGS5 expression in pericytes is observed in pathological hypoxic environments (e.g. tumours and ischaemic stroke) and associated with perivascular depletion of pericytes and vessel leakage." (PMID 36111549, 2022). "We have previously observed that loss of RGS5 in vivo resulted in increased numbers of pericytes in the infarct core 24 h after ischaemic stroke." (PMID 36111549, 2022). "Overall, RGS5 early expression in pericytes might contribute to the subsequent endothelial cell death and TJ loss after ischemic stroke." (PMID 39053491, 2025). "Interestingly, however, RGS5 increases dramatically in pathological hypoxia (e.g. in tumours or ischaemic stroke), where it is associated with pericyte detachment and migration from the capillaries into the brain parenchyma, resulting in BBB leakage." (PMID 36111549, 2022). "The vascular redistribution of PDGFRβ+ pericytes upon RGS5 depletion after ischemic stroke enhances angiogenesis, while reducing microvascular permeability." (PMID 38769116, 2024). "In turn, we and others have previously shown that when RGS5 is knocked out in models of ischaemic stroke or tumours, pericyte coverage of the vascular wall and vessel integrity are preserved and vascular leakage is substantially reduced." (PMID 36111549, 2022). "In vascular pathology like ischaemic stroke, tissue oxygenation is severely disturbed, leading to severe hypoxia and likely fast stabilization kinetics of RGS5, where its effects remain mostly unexplored." (PMID 36111549, 2022). "Here, we utilize RGS5 reporter mice in order to characterize the specific molecular pericyte response and potential differences between subpopulations of pericytes within the vascular niche in ischemic stroke at different timepoints of the acute ischemic cascade." (PMID 37378751, 2024).
gastric cancer (4 papers, 2019 to 2025). A primary or metastatic malignant neoplasm involving the stomach. "In gastric carcinoma and nonsmall cell lung carcinoma, RGS5 expression was positively correlated with tumor differentiation, and low RGS5 expression was associated with aggressive properties." (PMID 31049219, 2019). "RGS3 does not appear to be associated with prognosis in patients with gastric cancer, whereas RGS5, which has been shown to be associated with abnormal vascular formation, is a prognostic risk factor in three gastric cancer cohorts." (PMID 38693916, 2024). "Similarly, the expression of RGS5 is positively correlated with the degree of differentiation of gastric cancer." (PMID 35036167, 2021). "The key genes included in the LASSO-Cox regression model (including SPARC, EFEMP1, RGS5 and SERPINE1) were significantly upregulated in gastric cancer compared to the normal tissue." (PMID 41584584, 2025). "qPCR analysis revealed that the significant expressions of SPARC, EFEMP1, RGS5 and SERPINE1 were significantly upregulated in gastric cancer tissues compared to the normal tissues." (PMID 41584584, 2025).
bladder cancer (3 papers, 2019 to 2024). "Previous studies had explored the associations between RGS family members and bladder cancer risk, including RGS1, RGS2, RGS4, RGS5, RGS6, and RGS20." (PMID 34482807, 2021). "Three SNPs [rs2344673 (RGS5), rs3756712 (PDCD6), and rs2293347 (EGFR)] were associated with events of bladder cancer death, albeit in different subgroups." (PMID 31681611, 2019).
Cirrhosis (3 papers, 2014 to 2025). A chronic disorder of the liver in which liver tissue becomes scarred and is partially replaced by regenerative nodules and fibrotic tissue resulting in loss of liver function. "Pseudotime analysis also suggested that PDGFRα+ CAFs and RGS5+ CAFs from cirrhosis and HCC patients also diverged from HPCs, as we found in the rat HCC model." (PMID 39827226, 2025). "Enhancing the expression of RGS5 in HSCs could reduce their activation and subsequent development of fibrosis and cirrhosis." (PMID 25290689, 2014). "RGS5 inhibition of ET-1 signaling has potential in the treatment of liver fibrosis and cirrhosis." (PMID 25290689, 2014). "Focusing on the HSCs, which is the stromal cluster 0 and RGS5+, we noticed that HSC proportion was further enhanced in the HCC tissue compared to the cirrhosis." (PMID 33532508, 2021).
Hepatic steatosis (3 papers, 2012 to 2021). Steatosis is a term used to denote lipid accumulation within hepatocytes. "We determined the effect of RGS5 deficiency on obesity, hepatic steatosis, inflammation and insulin resistance in mice fed either a normal-chow diet (NC) or a high-fat diet (HF)." (PMID 22272317, 2012). "Our data suggest that loss of RGS5 exacerbates HF-induced obesity, hepatic steatosis, inflammation and insulin resistance." (PMID 22272317, 2012).
liver cancer (3 papers, 2016 to 2026). An epithelial or non-epithelial malignant neoplasm that arises from the liver. "To date, 20 canonical RGS genes (RGS1-RGS20) have been reported and a few members of the RGS family (RGS3, RGS5, RGS17) have also been associated with liver cancer." (PMID 36009801, 2022). "Tumor metastasis mediated by RGS5 occurs through induction of the epithelial–mesenchymal transition in liver cancer cells." (PMID 27105500, 2016).
liver diseases (3 papers, 2014 to 2022). "ET-1 and AngII-mediated sinusoidal constriction by HSCs induces portal hypertension; loss of RGS5 expression enhances GPCR signaling in response to these agonists, and may thus result in sinusoidal constriction." (PMID 25290689, 2014). "RGS5 expression is increased in multiple cancers (e.g., breast, ovarian, acute myeloid leukemia, and liver) and expression of Rgs5 in rodents can also lead to other liver diseases." (PMID 36687508, 2022). "Moreover, expression of a number genes—potential therapeutic targets in liver diseases—including EGFR, GLUD1, GNL3, and RGS5, has been shown to be modified by dietary fats and should be further investigated in this regard." (PMID 32961898, 2020). "We propose that in the absence of RGS5 expression in HSCs, HSCs are increasingly sensitive to GPCR agonists, such as ET-1 and AngII, which contribute to HSC activation, portal hypertension, and the severity of fibrosis." (PMID 25290689, 2014).
neuroblastoma (3 papers, 2012 to 2025). Neuroblastoma (NB) is the most common solid, extracranial childhood tumor. "Survival analysis in the same cohort of 101 neuroblastoma tumors showed association of decreased mRNA expression levels of both RGS5 and RNF11 with poor survival (p = 4.8E-2; p = 6.4E-4), which is in line with the observed association of both genes with MYCN expression." (PMID 23308108, 2013). "The in vivo role of RGS5 in neuroblastoma tumor vascularity is currently under further investigation." (PMID 23308108, 2013). "In addition, analysis of the 498SEQC dataset showed that RGS5, NDUFA4L2, and COX4I2 are all significantly correlated with EPAS1 expression in neuroblastoma." (PMID 41118218, 2025).
Obesity (3 papers, 2012 to 2022). Accumulation of substantial excess body fat. "To examine the association of the Rgs5 gene and inflammation with obesity, we investigated the gene expression of inflammatory mediators in major insulin-responsive tissues of mice fed an HF." (PMID 22272317, 2012). "This study is the first to clarify the role of RGS5 in obesity-associated metabolic dysfunction and insulin sensitivity." (PMID 22272317, 2012). "Although fatty acid oxidation is strengthened in insulin-sensitive organs, including adipose tissue and skeletal muscle in KO mice fed an HF, increased obesity and body weight maybe associated with the increased food intake induced by RGS5 deletion." (PMID 22272317, 2012). "RGS5 KO mice exhibited increased obesity, fat mass and ectopic lipid deposition in the liver compared with littermate control mice, regardless of diet." (PMID 22272317, 2012). "The present study used a diet-induced obesity paradigm with RGS5 KO and WT mice." (PMID 22272317, 2012). "Our findings the first demonstrate that RGS5 plays a critical role in the metabolic regulation of the body and maybe an important treatment target to obesity in the future." (PMID 22272317, 2012). "Next, we determined whether RGS5 plays a role in mediating obesity-induced insulin resistance." (PMID 22272317, 2012). "So it is not surprising that the RGS5 KO mice showed weakened insulin sensitivity because obesity and obesity associated higher levels of lipids and inflammation in circulation and tissues can directly and indirectly destroy insulin signaling in multiple sites." (PMID 22272317, 2012). "Although the present results clearly indicate RGS5 is an important protein in obesity and insulin resistance and also point to several possible mechanisms, there are some questions remain unknown and require further study, especially the reasons of increased food intake and energy consumption." (PMID 22272317, 2012). "However, the role of RGS5 in obesity and associated metabolic disorders is not clear." (PMID 22272317, 2012). "We hypothesized that the absence of RGS5 should modify the development of obesity and alter metabolic state during an HF and used RGS5 knockout (KO) and wild-type (WT) mice to demonstrate this hypothesis." (PMID 22272317, 2012). "Furthermore, RGS5 deletion increased the activation of both the JNK and NF-κB pathways in the adipose tissue, liver and skeletal muscle of obese mice, which are the two critical signaling pathways of inflammation induced by obesity." (PMID 22272317, 2012).
renal cell carcinoma (3 papers, 2019 to 2022). "In renal cell carcinoma, strong expression of RGS5 was observed in the vascular endothelium of the tumor stromal area compared with the expression in the vascular of the normal kidneys." (PMID 31049219, 2019).
triple-negative breast carcinoma (3 papers, 2023 to 2025). An invasive breast carcinoma which is negative for expression of estrogen receptor (ER), progesterone receptor (PR), and human epidermal growth factor receptor 2 (HER2). "We showed that higher RGS5 expression and blood vessel network co-existed in the triple-negative breast cancers (TNBCs) that constituted the most frequent type of invasive breast cancer." (PMID 37986113, 2023). "RGS5 expression was increased in the triple-negative breast cancer (TNBC) tissues and in the tumor blood vessels, accompanied with an extensive vascular network." (PMID 37986113, 2023). "RGS5 expression in the triple-negative (TNBCs) and non-triple-negative breast cancers (Non-TNBCs) was determined by immunofluorescent and immunohistochemical staining." (PMID 37986113, 2023).
cervical cancer (2 papers, 2022 to 2025). A primary or metastatic malignant neoplasm involving the cervix. "Our results suggested that RGS5 is up-regulated in cervical cancer, but its molecular biological function needs further investigation." (PMID 36561319, 2022). "Initially, we identified five necrosis-related lncRNAs, including lncRNA DDN-AS1, lncRNA DLEU1, lncRNA RGS5, lncRNA RUSC1-AS1, and lncRNA TMPO-AS1, for the construction of a signature that independently predict cervical cancer prognosis." (PMID 36561319, 2022).
coronary artery disease (2 papers, 2023 to 2024). "It is also known that the downregulation of RGS5 impairs endothelial cell function and contributes to coronary artery disease." (PMID 38396938, 2024). "The downregulation of RGS5 promoted inflammation in endothelial cells and impaired their normal function in contributing to coronary artery disease." (PMID 36982915, 2023).
glioma (2 papers, 2015 to 2025). A benign or malignant brain and spinal cord tumor that arises from glial cells (astrocytes, oligodendrocytes, ependymal cells). "GL261 mouse glioma was orthotopically implanted in mice expressing green fluorescent protein (GFP) under the pericyte marker regulator of G protein signaling 5 (RGS5)." (PMID 25875288, 2015). "Interestingly, even though intratumoral RGS5 positive pericytes aligned close to cells expressing the pro-angiogenic factor VEGF-R, known to play a major role in glioma angiogenesis and possibly invasiveness, pericytes activated in response to glioma growth did not express VEGF-R themselves." (PMID 25875288, 2015).
heart failure (2 papers, 2015 to 2023). Inability of the heart to pump blood at an adequate rate to meet tissue metabolic requirements. "Additionally, a study that explored the effects of the regulator of G protein signaling 5 (Rgs5) on cardiac remodeling and heart failure showed a protective role of Rgs5 in the presence of pressure overload which was attributed to the inhibition of MEK1/2-ERK1/2 pathway." (PMID 26257652, 2015).
ischemia (2 papers, 2014 to 2019). A hypoperfusion of the BLOOD through an organ or tissue caused by a PATHOLOGIC CONSTRICTION or obstruction of its BLOOD VESSELS, or an absence of BLOOD CIRCULATION. "In response to ischemia, pericytes are first activated as shown by increased expression of RGS5 and NG2." (PMID 24848101, 2014). "RGS5 may be a future target to enhance vascular repair and reduce BBB leakage after ischemia." (PMID 31039042, 2019).
liver cirrhosis (2 papers, 2021 to 2025). "Using the stellate cell marker—RGS5, we classified the stromal cluster 0 as hepatic stellate cells (HSCs) and noticed that compared with liver cirrhosis, the proportion of HSC in HCC tissue was further increased." (PMID 33532508, 2021). "Changes in the expression profile were observed between RGS5+ CAFs and PDGFRα+ CAFs in the pseudotime trajectory, GO enrichment analyses of BP terms revealed that PDGFRα+ CAFs from patients with liver cirrhosis and HCC were enriched mainly in functions related to the inflammatory response." (PMID 39827226, 2025).
lymph node metastasis (2 papers, 2019 to 2020). "They detected a high RGS5 expression in 47% of NSCLC patients, and low expression of RGS5 has been observed to be linked with cancer vasculature invasion and lymph node metastasis." (PMID 32431860, 2020). "Kaplan–Meier analysis revealed that high RGS5 expression was associated with postoperative early lymph node metastasis." (PMID 31049219, 2019). "In terms of RGS5 expression and postoperative lymph node metastasis, early postoperative lymph node metastasis tended to occur in the RGS5 high expression group, but the lack of a significant difference may be related to the small number of cases (n = 43) and short postoperative observation period." (PMID 31049219, 2019).
melanoma (2 papers, 2020 to 2024). A malignant, usually aggressive tumor composed of atypical, neoplastic melanocytes. "While all three stromal populations expressed fibroblast markers, indicating that they represent melanoma CAFs, S3 also expressed some pericyte-associated markers such as Cspg4 (Ng2), Mcam, and Rgs5." (PMID 32433953, 2020). "Melanoma CAF subpopulations usually include iCAFs and myCAFs, however, a number of other unique clusters have been put forth including, distinct ECM and contractile CAFs in, Wif1 and Zeb2 subpopulations, and matrix and RGS5." (PMID 38525245, 2024).
non-small cell lung carcinoma (2 papers, 2020 to 2022). A group of at least three distinct histological types of lung cancer, including non-small cell squamous cell carcinoma, adenocarcinoma, and large cell carcinoma. "On the other hand, a strong association has been observed between high RGS5 expression level and better survival in 51 non-small cell lung cancer (NSCLC) patients." (PMID 32431860, 2020).
scleroderma (2 papers, 2008 to 2021). Scleroderma is a rare autoimmune connective tissue disorder characterized by abnormal hardening of the skin and, sometimes, other organs. "The apparent loss of capillaries in scleroderma led us to look for increased expression of RGS5 mRNA." (PMID 18197262, 2008). "RNA in situ hybridization for RGS5 at baseline shows that 6 of 7 scleroderma patients had increased positive cells (p = 0.0023)." (PMID 18197262, 2008). "We found that both RGS5 mRNA expression was significantly increased in scleroderma." (PMID 18197262, 2008). "This indicate that decreased RGS5 expression after HDIT/HCT is insufficient to regenerate capillaries by itself, but like the VE Cadherin data may suggest that some form of vasostatic process in scleroderma inhibited any angiogenic response prior to treatment." (PMID 18197262, 2008).
skin cancer (2 papers, 2024). "While the presence of these subsets seems to depend on the skin cancer type with iCAFs being associated with the most aggressive tumors, RGS5+ cells were found in all tumor samples independently of skin cancer type and malignancy." (PMID 39516494, 2024).
squamous cell carcinoma (2 papers, 2019 to 2024). A carcinoma arising from squamous epithelial cells. "We examined RGS5 expression and its relationship with invasion in squamous cell carcinoma (SCC) of the tongue." (PMID 31049219, 2019).
acute respiratory distress syndrome (1 paper, 2021). Progressive and life-threatening pulmonary distress in the absence of an underlying pulmonary condition, usually following major trauma or surgery. "Using RGS5 knockout animals, we found a selective effect of RGS5 on the neutrophilic inflammatory response in the early phase of acute respiratory distress syndrome (ARDS)." (PMID 34502263, 2021).